IDH1 (isocitrate dehydrogenase (NADP(+)) 1)
Diseases named in the same sentence as IDH1 in open-access papers (continued):
Sharing a sentence is not in itself a finding about the gene and the disease.
glioma (continued). "Overall, there was a significant reduction in the number of methylated loci in both TS603 and TS667 glioma cells, although the degree of hypomethylation was more pronounced in the IDH1-wild-type TS667 line." (PMID 24077826, 2013). "The analysis was performed using genomic DNA obtained from both early and late passage xenograft tissue (passages 1, 7 and 10) as well as two unrelated IDH1 (R132H) anaplastic astrocytoma samples and three IDH1 (WT) glioma primary patient samples as controls." (PMID 24077805, 2013). "In conclusion, this study demonstrated a strong tendency of IDH1/IDH2 status being consistent during progression of glioma." (PMID 23840696, 2013). "This study reviewed 60 patients with histologically confirmed low-grade gliomas, and the status of IDH1 was detected after the operation at our institution." (PMID 24324372, 2013). "Our studies also indicate that growth of IDH1 wild-type glioma cells are reduced following transient treatment with DAC, albeit through alternate pathways." (PMID 24077826, 2013). "The functional consequences of IDH1 mutations and a role in the establishment of the glioma-CIMP (G-CIMP) has been explored using immortalised primary human astrocytes and isogenic cells expressing either mutant or wild-type IDH1." (PMID 22771539, 2013). "All of the primary gliomas showed consistent IDH1/IDH2 status as the corresponding recurrent gliomas, includingthe three cases of rare mutant (IDH1-R132S, IDH1-R132G and IDH2-R172K)." (PMID 23840696, 2013). "These glioma-CpG island methylator phenotype (G-CIMP) tumors belonged to the proneural subgroup and were tightly associated with IDH1 somatic mutations, and patients were younger at the time of diagnosis and had improved outcomes." (PMID 24202336, 2013). "Six glioma cases possessed a mutant IDH1 or a mutant IDH2, and 12 cases had wild-type IDH1 and IDH2." (PMID 23456655, 2013). "It remains unfortunate that only a limited number of endogenous IDH1-R132H mutant glioma models is currently available making it difficult to confirm our findings in other models." (PMID 24252742, 2013). "JHH-273 produced high levels of 2-HG which correspond to the endogenous levels reported in IDH1/2 mutant gliomas." (PMID 24077805, 2013). "The efficacy of using DNA demethylating agents to treat mutant IDH1 expressing glioma cells has yet to be tested." (PMID 24077826, 2013). "In this review, we summarize the frequency and role of IDH1 and IDH2 mutations in gliomas and myeloid neoplasms, the latter with an emphasis on AML, and the association of these mutations with clinical, morphologic, cytogenetic, and molecular characteristics." (PMID 23847760, 2013). "After a 2-week exposure to 200 nM DAC, 30,915 probes (corresponding to 9996 unique genes) were hypomethylated in IDH1 mutant TS603 glioma cells and 130,017 probes (corresponding to 17,182 unique genes) were hypomethylated in TS667 cells (Δβ value < -0.4)." (PMID 24077826, 2013). "IDH1 and IDH2 mutations are well known in gliomas, but are notoriously difficult to grow in culture." (PMID 22928481, 2012). "It has been reported that IDH1 (IDH1R132) mutation was a frequent genomic alteration in grade II and grade III glial tumors but rare in primary glioblastoma (pGBM)." (PMID 22291938, 2012). "Further studies confirmed that mutant IDH1 impairs histone demethylation and is sufficient to establish the glioma hypermethylator phenotype, resulting in a block to cell differentiation." (PMID 22885298, 2012).
glioma (continued). "The capability of IDH mutations to induce oxidative intracellular conditions is linked to a decrease in GSH levels, observed both in IDH1-R132H—and IDH2-R172K—expressing glioma cells with respect to their wt counterparts." (PMID 22888353, 2012). "Regional molecular heterogeneity about chromosome 1p/19q and IDH1/2 in gliomas reported in English literature." (PMID 22427879, 2012). "To date, results from structural and functional assays by several multicenter trials suggested that IDH1 R132, which resides at the active site of enzyme substrate affinity, promotes oncogenesis in both glioma and AML." (PMID 22397365, 2012). "Thalidomide had the ability to induce IDH1 gene expression, Isocitrate dehydrogenase (IDH)-1 mutations are associated to glioma development." (PMID 22695124, 2012). "Recent studies also proved that IDH1 or IDH2 mutations predicted longer survival and response to temozolomide in low-grade gliomas." (PMID 22291938, 2012). "The identification of monoallelic expression of IDH1 in glioma raises potential issues in the clinical interpretation of these molecular analyses." (PMID 23267435, 2012). "Glial-appearing IDH1-immunoreactive cells were found surrounding vascular structures in many tumors, consistent with the known predilection of infiltrating gliomas to satellite around blood vessels." (PMID 22298889, 2012). "In fact, oligodendroglioma, a tumor type which were nearly all mutant for IDH1 in our cohort, showed the highest level of staining for 5hmC among infiltrating gliomas." (PMID 22829908, 2012). "While one group reported increased growth in vivo in a melanoma cell line transfected with mutant IDH1, another group reported a decrease in proliferation in glioma cell lines both in vitro and in vivo in the presence of mutant IDH1." (PMID 22885298, 2012). "This demonstrates for the first time to our knowledge that gliomas with IDH2 R172 mutations can have elevated 2HG, that any cancer with IDH1 R132L or IDH2 R172M have elevated 2HG, and that 2HG in cancer tissues is specific for (R)-2-hydroxyglutarate." (PMID 21326614, 2011). "The IDH1 mutation is expected to be almost mutually exclusive with EGFR amplification, so glioma cells with IDH1 mutations seem to represent a new group of tumour cells, which cannot be readily analysed in vitro because of their elimination." (PMID 21326241, 2011). "Several different amino acid substitutions recur at either IDH1 R132 or IDH2 R172 in glioma patients." (PMID 21326614, 2011). "Both IDH1 and IDH2 mutations are more frequent in grade II-III gliomas and secondary glioblastoma (70–75%) than in primary glioblastoma (5%), are present at higher frequencies in younger patients, and are associated with a relatively favourable prognosis." (PMID 21625441, 2011). "Apart from frequent mutations in the IDH1/2 gene, much less is known about the causal genetic changes of grade II and III (anaplastic) gliomas." (PMID 24212656, 2011). "The molecular mechanism by which IDH1 mutations and ALT are associated in Glioma remains to be understood." (PMID 22046342, 2011). "To do so, we first transfected glioma cells with combinations of IDH1-WT and IDH1-R132H with MYC-FLAG or EGFP tags." (PMID 21326614, 2011).
glioma (continued). "In contrast, proneural tumors frequently harbor PDGFRA amplification or IDH1 mutations; the latter are characteristic of IDH-mutant gliomas and are associated with the CpG island methylator phenotype (G-CIMP), frequent MGMT promoter methylation, and comparatively favorable clinical outcomes." (PMID 41596524, 2026). "Nevertheless, the difference of brain T values between the naïve, IDH1‐wild‐type and IDH1‐mutant groups may demonstrate the effect of glioma on the whole brain." (PMID 41436375, 2026). "IDH1‐mutant gliomas are typically less aggressive and more responsive to therapy than wild‐type gliomas, resulting in improved prognosis for patients; meanwhile, wild‐type gliomas have a median overall survival time of only 12 months, with less than 5% of patients surviving to 5 years." (PMID 41436375, 2026). "A more thorough exploration of this trend evaluated temporally with a larger sample size may help us to better understand the brain's response to glioma and IDH1 typing." (PMID 41436375, 2026). "This study aimed to evaluate the association of IDH1 (R132H) IHC as a surrogate marker within the World Health Organization (WHO) integrated framework and to correlate the expression of IDH1 (R132H) with clinicopathological parameters in gliomas." (PMID 41994675, 2026). "Our findings suggest that executive functioning in patients with IDH1-mutant low-grade gliomas may differ based on tumor subtype." (PMID 41514682, 2026). "Moreover, inhibitors focused on metabolic reprogramming at the IDH1/2-mutant gliomas are under investigation." (PMID 41514664, 2026). "Isocitrate dehydrogenase type 1 (IDH1) serve as specific molecular markers in gliomas." (PMID 40661781, 2025). "This means that some IDH1-wildtype gliomas may be misclassified as mutant, potentially leading to inappropriate treatment decisions." (PMID 40299088, 2025). "Moreover, the HIF1α- tenascin C (TNC) feedback loop has been identified as a key regulator of ECM stiffness and glioma aggression, with mutant IDH1 suppressing HIF1α expression and reducing TNC deposition." (PMID 40076738, 2025). "The H2O2/GSH ratio mapping of live glioma cells clearly differentiates their IDH1 genotype." (PMID 40171868, 2025). "Most of the patients (86–92%) in the TCGA database had GBM that was associated with poorer overall survival (mean survival days 502–407 days) than IDH1-mutant glioma in both the RNA-seq and microarray datasets (mean survival 969–723 days); these results are consistent with those of another study." (PMID 40057744, 2025). "Our results suggest that IDH1 mutation status significantly impacts responsiveness to RNaseH2 inhibition, particularly in combination with TMZ, supporting a more personalized treatment approach to improve outcomes for glioma patients." (PMID 41285884, 2025). "Another factor contributing to the low specificity values may be the inherent heterogeneity and radiogenetic variability in gliomas, making it challenging to distinguish between IDH1-positive and IDH1-negative cases consistently." (PMID 40299088, 2025). "Regarding glioma subtype-specific clinical implications, we found that ESURATAG-GS expression is associated with higher tumor grade in IDH1-Mut tumors, ODGs, ATCs and IDH1-WT tumors in TCGA dataset." (PMID 40718795, 2025). "According to age distribution, GBM patients exhibited the oldest median age at diagnosis (52 years), followed by patients with IDH1/2-wild-type glioma (39 years), patients with oligodendroglioma (44 years), and patients with IDH1/2-mutant astrocytoma (38 years)." (PMID 41377022, 2025). "Notably, the point mutations in IDH1/2 found in CS often differ from those observed in other tumors, including acute myeloid leukemia (AML) and glioma." (PMID 40867318, 2025). "Mutations in the IDH1 and IDH2 genes are present in glioma at varying rates." (PMID 40564017, 2025).
glioma (continued). "Proline biosynthesis is documented to support redox homeostasis in IDH1-mutant glioma by reducing the NADH/NAD + ratio via PYCR1 activity, which enables continuation of TCA cycle activity when flux through the electron transport chain is limiting as seen in hypoxic conditions." (PMID 39816516, 2025). "Collectively, the findings from patient 15 hint at the lack of a hypoxia-induced metabolic phenotype, supporting the observations of Kickingereder and colleagues of strong inhibition of HIF1A and decreased expression of HIF1α target genes in IDH1 mutant gliomas." (PMID 39816516, 2025). "SIRT7 influences glioma progression by regulating IDH1 expression and metabolic pathways." (PMID 40710366, 2025). "Isocitrate dehydrogenase is a metabolic enzyme found in glioma and non-nervous system tumors that has five isotypes, with IDH-1 and IDH-2 comprising most mutations in glioblastoma." (PMID 40422257, 2025). "If we first look at gene pair RBP1-BMP2, it has been found that RBP1 shows reduced expression in many prevalent cancers and that in the Chinese Glioma Population Database (CGGA), RBP1 was one of the eight identified hub genes associated with IDH1 mutant status." (PMID 39941811, 2025). "Furthermore, the ROC curve of the H2O2/GSH incorporated logistic regression model indicated the performance of Au‐R12P in classifying glioma IDH1 genotypes in clinical settings, with an AUC of 0.9851." (PMID 40171868, 2025). "In addition, the confusion matrix confirmed that Au‐R12P has great diagnostic performance in determining IDH1 genotypes (Predictive accuracy: 96.4% for IDH1‐MUT glioma; 94.1% for IDH1‐WT glioma)." (PMID 40171868, 2025). "Therefore, by reducing the glucose level in the postoperative environment and increasing the generation of ROS, it is expected to inhibit the recurrence of IDH1 (R132H) glioma." (PMID 40371327, 2025). "Moreover, the dynamic workflows described here transcend static targeting, even when considering IDH1-mutant gliomas with regional hypoxia and HIF1α-augmented YAP1 signaling." (PMID 40806492, 2025). "Eleven glioma cases were classified as glioma NOS because genetic analysis showed no IDH1/2, TERT promoter, or H3-3A mutations." (PMID 41163986, 2025). "Moreover, mutations in IDH1 and IDH2, recurrently observed in gliomas and acute myeloid leukemias, lead to the neomorphic production of 2-hydroxyglutarate (2HG), a competitive inhibitor of αKG-dependent dioxygenases." (PMID 41411367, 2025). "Of the 48 gliomas, 22 cases (45.8%) were IDH1 mutant, while 26 cases (54.2%) were IDH1 wild type." (PMID 40944023, 2025). "However, only 32% of patients with low-grade IDH1/2-mutant gliomas and 52% of patients with high-grade IDH1/2-mutant gliomas have been assessed for MGMT-methylation status." (PMID 39164213, 2025). "However, the precise mechanism by which the IDH1-mutant metabolite, R-2HG, suppresses inflammatory activation in gliomas remains to be elucidated." (PMID 41367876, 2025). "In addition, in gliomas, PIEZO1 expression was also associated with patient age, histopathological subtype, IDH1 mutation status, and chemotherapy." (PMID 40724850, 2025). "Lower-grade gliomas, such as grades II and III, had a higher IDH1/2 mutation frequency of 70–80%." (PMID 40564017, 2025). "However, the proportion of IDH1/2-wild-type gliomas in the thalamus–basal ganglia (13.9%) and the infratentorial region (14.5%) was significantly higher than that of IDH1/2-mutant gliomas (3.3% and 3.2%, respectively)." (PMID 41377022, 2025). "mu/IDH1 has been shown to play a role in the remodelling of the methylome in gliomas." (PMID 40182999, 2025).
glioma (continued). "IDH1 may play a role in the development of intracranial lesions as it is not only involved in driving the formation of gliomas, but also can impair differentiation by increasing apoptosis in various central nervous system lineages, leading to neuronal defects." (PMID 39634128, 2025). "In this regard, our study demonstrated a higher frequency of non-canonical IDH1 (p.R132S) mutations as a proportion of the IDH-mutant gliomas, compared to an European population (34% vs. 10%)." (PMID 41567539, 2025). "This AI‐assisted SERS approach can identify the IDH1 genotype in glioma patients within 7 min." (PMID 40171868, 2025). "Multiple follow-up samples were taken from eight patients with IDH1-mutant glioma." (PMID 40285800, 2025). "In this study, we proposed a fully automated method to predict IDH1 mutation in patients with glioma, requiring no user intervention, and proving highly suitable for clinical practice." (PMID 40134593, 2025). "Patients with a known diagnosis of IDH1-mutant glioma who required surgery for tumor recurrence were randomized to receive vorasidenib (at a dose of either 10 or 50 mg daily), ivosidenib (either 250 mg twice daily or 500 mg daily), or no treatment prior to surgery." (PMID 40867259, 2025). "Importantly, CD133—a marker of stemness—has been found to be upregulated in high-grade IDH1-mutant gliomas, further linking mutant IDH metabolism to cancer stem cell maintenance." (PMID 40724998, 2025). "Notably, IDH1‐MUT glioma tissues exhibited higher concentrations of H2O2 compared to IDH1‐WT tissues." (PMID 40171868, 2025). "Taken together, IDH1 appears to be the strongest predictor for VTE in glioma patients." (PMID 39851266, 2025). "The IDH1 wild type glioma may result in elevated expression of hypoxia-inducible factor-1, subsequently increasing the expression of angiogenic factors in hypoxic tissues." (PMID 40944023, 2025). "While the IDH1R132H mutation is the most common, accounting for over 90% of IDH-mutant gliomas, non-canonical IDH1 mutations have also been associated with improved survival outcomes." (PMID 41346390, 2025). "The results indicated IDH1 mutate, 1P19 codeletion, ATRX and MGMT as robust favorable clinical prognostic indicators, while PCK2 along with age (PCK2, TCGA: P<0.0001, CGGA: P<0.0001) serve as indicators for poor survival time in glioma patients." (PMID 39744481, 2025). "Our cohort included 355 cases of GBM (44.5%), 179 cases of astrocytoma (22.4%), 135 cases of oligodendroglioma (17.0%), and 129 cases of other IDH1/2-wild-type gliomas (16.1%), all classified according to the WHO classification of tumors of the CNS 2021 guidelines." (PMID 41377022, 2025). "Our study demonstrated that KNN and Ensemble models exhibited the highest classification performance, with KNN achieving 92.59% accuracy, 100% precision, and an AUC of 0.90, making it the most reliable model in distinguishing IDH1-positive and IDH1-negative gliomas." (PMID 40299088, 2025). "Amongst all patients ≥20 years old with primary gliomas, the median survival varied across glioblastoma (18.0 months, range: 0.1–164.0 months), IDH1/2-mutant astrocytoma (118.5 months, range: 0.1–262.2 months), and oligodendroglioma (213.9 months, range: 0.1–324.4 months)." (PMID 39164213, 2025).